CYP2E1 (cytochrome P450 family 2 subfamily E member 1)
Diseases named in the same sentence as CYP2E1 in open-access papers (continued):
Sharing a sentence is not in itself a finding about the gene and the disease.
diabetes (37 papers, 2009 to 2025). "CYP2-E1 has been implicated in different pathological conditions such as diabetes and cancer, possibly due to its capacity to generate high levels of ROS." (PMID 38087036, 2024). "The CYP2E1 has been suggested to be associated with drug metabolism and cancers, liver conditions, diabetes, SCZ, Parkinson’s disease, cognitive and neurobiological phenotypes." (PMID 36494682, 2022). "CYP2E1 is also involved in ROS production in mitochondria and this capacity is believed to result in lipid peroxidation, which is associated with the etiology and pathology of many diseases, including diabetes." (PMID 37428327, 2023). "Interestingly, NF-κB regulates CYP2E1 expression by different ways, being implicated in several diseases including diabetes." (PMID 26063976, 2015). "An increased CYP2E1 expression in various tissues of STZ-induced diabetic rats including the liver has been reported recently.During diabetes, the elevated CYP2E1 level may be an important risk factor for oxidative stress." (PMID 24719626, 2013). "In this work, we investigated the effect of long-term consumption of omega-3-enriched pharmaceutical composition of PUFAs on the level of CYP2E1 expression as a key factor in the initiation and development of liver pathology in diabetes mellitus." (PMID 36225205, 2022). "Therefore, the question arises whether long-term treatment with CYP2E1 substrates may increase the risk of developing CYP2E1-dependent oxidative stress in some diseases (including diabetes) whose pathogenesis is closely associated with increased expression of CYP2E1." (PMID 36225205, 2022). "Increased CYP2E1 expression in diabetes is related to increased production of ROS and, consequently, the formation of oxidative damage." (PMID 34576213, 2021). "Data from primary cultured rat hepatocytes demonstrated that insulin decreased the expression of CYP2E1 and CYP2B protein and mRNA, inferring that a deficiency of insulin is also a reason that diabetes induces the expression of CYP2El and CYP2B." (PMID 32290519, 2020). "Diabetes increased the expression of CYP2E1 and CYP3As by 3-fold and the expression of CYP2C11 mRNA was decreased to 16% that of control rats." (PMID 32290519, 2020). "Expressions of other CYP450s, such as CYP1B1, CYP2B1, CYP2C11 and CYP2E1, were unaltered, inferring that diabetes regulates the expression of hepatic CYP450s in an isoform-specific manner." (PMID 32290519, 2020). "Cyp2e1 is also expressed in lymphocytes of human diabetes patients (Hannon‐Fletcher, O'Kane, Moles, Barnett, & Barnett, 2001)." (PMID 31429526, 2019). "Quantitated amounts of CYP2E1 protein in the pre-diabetes and diabetes groups showed significant difference relative to control group (p < 0.001)." (PMID 27376033, 2016). "Recent studies have also showed that CYP2E1 expression in peripheral lymphocytes is elevated in diabetes and kidney disorders." (PMID 27376033, 2016). "Increase in the expression of particularly CYP2E1 isozymes in diabetic animals, is seen as an adaptation for the elimination of oxidative products and the pathology of diabetes." (PMID 25905778, 2015). "Increased expression of hepatic CYP2E1 in human or experimental diabetes and alcohol abusers has been reported." (PMID 26063976, 2015). "Previous report has shown that the expression of CYP2E1 messenger (m) RNA and protein is increased during diabetes." (PMID 24719626, 2013). "Nevertheless, similarities between ethanol-induced increased CYP2E1 and fatty liver damage and nonalcoholic-induced liver steatohepatitis in diabetes suggest common mechanisms involving CYP2E1 and atRA." (PMID 20559430, 2010). "CYP2E1 P450 levels are increased in patients with NASH because fatty acids and ketone bodies including acetone, which increased in diabetes/ketosis, are substrates and inducers of CYP2E1 protein." (PMID 20300478, 2009). "Concerning diabetes, many studies have focused on CYP2E1 and CYP1A1 enzymes." (PMID 37428327, 2023).
diabetes (continued). "The very high glycemia and ketonemia in these mice might play a role in CYP2E1 induction in this context of severe diabetes." (PMID 36713231, 2023). "In diabetes, cytochrome P450 2E1 (CYP2E1) overexpression is observed at protein and mRNA levels." (PMID 34576213, 2021). "It is hypothesized that in the case of fat mobilisation as in diabetes mellitus, the hyperketonemia and other small organic molecules are both substrates and inducers of CYP2E1 that will lead to non-alcoholic fatty liver disease." (PMID 33261113, 2020). "Both alloxan-induced diabetes and STZ-induced diabetes were reported to increase expressions of hepatic CYP2E1 and CYP3A2 by three-fold, leading to a lower area under the curve (AUC) of theophylline and a higher AUC of 1,3-dimethyluric acid following oral and intravenous administration to rats." (PMID 32290519, 2020). "Hyperketonemia (such as acetone) is considered as a reason for diabetes inducing CYP2E1." (PMID 32290519, 2020). "Hon inhibited the activity of CYP1A2 and CYP2E1 of diabetic rats dosage-dependently indicating that Hon could inhibit the activation of some pre-cancerogenic and toxic substances induced by diabetes, which had protective effect on body." (PMID 29534510, 2018). "For example, in subjects with prediabetes versus controls, cytochrome P450, family 4, subfamily F, polypeptide 3 (CYP4F3), CYP4F8, Phospholipase A2, group IIC (PLA2G2C), and PLA2G4E were differentially methylated, while in subjects with diabetes versus prediabetes, CYP2E1 and PLA2G12A were involved." (PMID 27555869, 2016). "So CYP2E1 and ROS are reciprocally modulated in diabetes and ethanol exposure." (PMID 26063976, 2015). "However, our finding that diabetes increased renal cortical levels of CYP2E1 is similar to recent observations in streptozotocin-diabetic rats, and offers a potential mechanism for increased metabolism of atRA." (PMID 20559430, 2010). "DAS, for instance, has been reported to serve as a selective inhibitor of cytochrome P450 2E1 (CYP2E1), and therefore it is not only able to inhibit the cellular toxicities associated with alcohol and xenobiotic drugs; it also limits the cellular toxicities associated with HIV proteins and diabetes." (PMID 35739933, 2022). "Thus it is possible that the phenolic and flavonoid compounds present in these extracts may act against the oxidative stress-related hepatotoxicity produced by the induction of CYP2E1 in STZ-induced diabetes and thereby protect the liver." (PMID 30545352, 2018). "The synergistic role of CYP2E1 and CYP4A11 in the saturated and unsaturated fatty acids metabolism indicates their vital role in fasting, diabetes, and the progression of MASLD." (PMID 40452921, 2024). "Both the CYP2E1 and Cyp4A14 genes are synergistically regulated by the nuclear transcription factor erythroid factor 2 (NRF2) during fasting, diabetes, high-fat diet, and ethanol intoxication." (PMID 40452921, 2024). "Regarding diabetes, while hepatic CYP1A1 and CYP2E1 activity and lipid peroxidation (LPO) were enhanced in STZ-induced diabetic rats, insulin treatment attenuated the enzyme activities and LPO levels." (PMID 37428327, 2023). "Diabetes altered expression of these targeted proteins (CYP2C11, CYP3As, CYP2E1 and OATs), intestinal blood, liver blood flow and renal blood flow." (PMID 32290519, 2020). "Growing evidence has demonstrated that diabetes increases the expression of some CYP450s (such as CYP2A1, CYP1A2, CYP2B1/2, CYP2C6, CYP2C7, CYP3A1/2 and CYP2E1) in rats, although opposite reports have also been shown." (PMID 32290519, 2020). "CYP1A2 and CYP2C9 activities showed a trend to slightly increase in subjects with diabetes, but activities of CYP2D6 and CYP2E1 were unaltered." (PMID 32290519, 2020). "Diabetes also changes the experesion of cytochrome P450 enzymes, including CYP3A4, CYP2E1, CYP2C9, and CYP2D4 participate in phase I drug metabolism." (PMID 32467722, 2020).
diabetes (continued). "Further studies would be needed in order to determine why hepatic CYP2E1 induction is not always observed in streptozotocin-induced experimental diabetes." (PMID 36713231, 2023). "Although various studies have convincingly dictated the association of CYP2E1 and reactive oxygen species (ROS) in diabetes and its complications, there is lack of evidence on the changing profile of ROS and CYP2E1 levels with varying glycemic levels." (PMID 27376033, 2016). "Since the second binding site in CYP2E1 is involved in fatty acid metabolism, we propose that BCM binding to this second site may impair fatty acid metabolism and may indirectly prevent normal metabolism of larger molecules that may be already impaired in chronic illnesses such as diabetes." (PMID 22719758, 2012).
Insulin resistance (31 papers, 2013 to 2025). Increased resistance towards insulin, that is, diminished effectiveness of insulin in reducing blood glucose levels. "Cytochrome P450 family 2 subfamily E member 1 (cyp2e1) is linked to insulin resistance and oxidative stress, contributing to non-alcoholic fatty liver disease, a condition with established associations to increased BC risk." (PMID 38827320, 2024). "Insulin resistance also causes increased gluconeogenesis, and CYP2E1 plays a leading role in these processes." (PMID 36225205, 2022). "CYP2E1 was recently shown to be linked to insulin resistance via the anti-apoptotic protein Bax inhibitor-1, which plays an important role in the regulation of CYP2E1." (PMID 34360999, 2021). "Mice deficient in CYP2E1 are protected from HFD-induced insulin resistance, oxidative stress and fibrosis, indicating a direct role of CYP2E1 in NASH and T2DM." (PMID 29874807, 2018). "An upregulation in CYP2E1 has also been associated with leptinemia, reduced adiponectin levels, and insulin resistance in NAFLD." (PMID 23346097, 2013). "Furthermore, the repressive effects of insulin on CYP2E1 levels are lost in insulin resistance, commonly associated with NAFLD and NASH." (PMID 34360999, 2021). "However, in the future, other studies are needed to elucidate if increased CYP2E1 is a cause or a consequence of insulin resistance." (PMID 25873773, 2015). "Increased hepatocyte CYP2E1 expression may also result in the downregulation of insulin signalling, potentially contributing to the insulin resistance associated with NAFLD." (PMID 25873773, 2015). "Moreover, the expression and activity of CYP2E1 is increased as a result of the high concentration of ketone bodies during insulin resistance in NAFLD10, which is one of the most important causes of the disorder in the pig liver." (PMID 26358367, 2015). "In addition, increased levels of circulating ketone bodies and acetone (substrates of CYP2E1) in the blood may cause an increase in CYP2E1 in the diabetic liver, leading to the development of insulin resistance." (PMID 36225205, 2022). "CYP2E1 hepatic overexpression increased oxidative stress, increased systemic insulin resistance, decreased insulin signaling in the liver, and increased hepatic fat accumulation." (PMID 40452921, 2024). "Cyp2e1−/− mice are protected from high-fat-induced insulin resistance with insulin, which is known to decrease Cyp2E1 expression." (PMID 40452921, 2024). "CYP2E1 is related to the regulation of oxidant stress, insulin resistance and fatty acids, and the expression of hepatic CYP2E1 enhanced in patients with NAFLD." (PMID 35528835, 2022). "A vicious cycle was postulated, starting with increased levels of fatty acids and insulin resistance promoting the expression of CYP2E1." (PMID 36528753, 2022). "Insulin resistance, in turn, contributes to the maintenance of high levels of CYP2E1 and the progression of oxidative damage in hepatocytes." (PMID 36225205, 2022). "On the one hand, liver CYP2E1 level is inducible, and can be upregulated by high levels of fatty acids, low levels of adiponectin, and the status of insulin resistance, which all pathophysiologically characterize NAFLD." (PMID 34461916, 2021). "CYP2E1 knockout mice exhibit a marked protection against high fat diet-induced insulin resistance with enhanced adipose tissue glucose uptake, insulin suppression of hepatic glucose output, and decreased proinflammatory cytokines from adipose tissues." (PMID 31275421, 2019). "Further, Cyp2e1 knockout mice are protected from HFD-induced insulin resistance, providing evidence to suggest that CYP2E1 does play a role in NAFLD progression and metabolic syndrome." (PMID 24379011, 2013).
Insulin resistance (continued). "Triterpene glycosides from loquat leaves can remodel the mouse gut microbiota by improving insulin resistance, modulating insulin signaling, and inhibiting the cytochrome P450 2E1 (CYP2E1) and NOD‐like receptor family pyrin domain‐containing 3 (NLRP3), ameliorating type 2 diabetes." (PMID 40599359, 2025). "In the context of MASLD, and given the addictive properties of alcohol, the claim for total alcohol abstinence is supported by a variety of mechanisms, including interaction with cytochrome P450 2E1 (CYP2E1), the coupled effects of high ethanol intake and insulin resistance on enhancing OS." (PMID 41155762, 2025). "Cyp2e1-deficient mice, moreover, were shown to be protected against DIO and insulin resistance." (PMID 40497936, 2025). "It is unknown whether insulin resistance in MASLD increases CYP2E1 by ketone bodies that stabilize CYP2E1 P450 and prevent its degradation by the ubiquitin-dependent proteasome system." (PMID 40452921, 2024). "The increased levels of CYP2E1 in return may induce lipid peroxidation, oxidative damage and aggravate insulin resistance, which is augmenting the fat accumulation in the liver." (PMID 36528753, 2022). "Although some findings suggest that insulin resistance might induce higher CYP2E1 expression and activity in NAFLD, further studies are required to determine whether this metabolic state specifically affects CYP2E1 targeting to mitochondria." (PMID 35053404, 2022). "In addition to increase hepatic lipid deposition, insulin resistance exacerbate liver oxidative stress by upregulating CYP2E1." (PMID 33882064, 2021). "Interestingly, a significant amount of CYP2E1 has been suggested to be localized within liver mitochondria, inducing mitochondrial dysfunction and insulin resistance and also suggesting the possibility of connected ROS signaling between the ER and mitochondria through CYP2E112." (PMID 27576594, 2016). "Central to this interaction is cytochrome P450 2E1 (CYP2E1), whose induction by both ethanol and insulin resistance enhances oxidative stress, lipid peroxidation, and fibrogenesis." (PMID 40647333, 2025). "A previous study showed that CYP2E1 plays a critical role in NASH development by promoting oxidative/nitrosative stress, protein modifications, inflammation, and insulin resistance." (PMID 39062078, 2024). "The functional stabilization of CYP2E1 induced hepatic oxidative stress, JNK1 signaling activation, insulin resistance, and accumulation of fatty acids and triglycerides, which results in liver injury, contributing to non-alcoholic steatohepatitis." (PMID 34055494, 2021). "To further explore the hepatoprotective mechanism of TF, we tested the expression of IRs-1, Akt, CYP2E1, and JNK in liver tissues, which are involved in insulin resistance and oxidative stress." (PMID 30275422, 2018). "Our study found that Hon significantly inhibited the activity of CYP2E1 and CYP4A of rats with T2DM, which might be one of the most important mechanisms that Hon decreased the oxidative stress injury and insulin resistance in diabetic rats." (PMID 29534510, 2018). "The loss of the repressive effect of insulin on the expression of CYP2E1 could be a possible link between OSAS, insulin resistance, and NASH." (PMID 25873773, 2015). "It has been hypothesized that some fatty acids, hyperleptinemia and insulin resistance might be involved but the downstream signaling pathways leading to CYP2E1 induction have not been characterized yet." (PMID 35053404, 2022). "This study identified CYP2E1 as a crucial player in ER stress-induced ROS production, supporting our hypothesis that the antagonistic activity of BI-1 against ER stress-induced insulin resistance in liver cells is due to inhibition of ROS via interconnection between CPR and CYP2E1." (PMID 27576594, 2016).